KRAS (KRas proto-oncogene, GTPase)
Diseases named in the same sentence as KRAS in open-access papers (continued):
Sharing a sentence is not in itself a finding about the gene and the disease.
cancer (continued). "Finally, a pooled shRNA screen in KRAS mutant cancer cells, which are dependent on MEK activation, found that inhibition of BCL-XL cooperated with MEK inhibitors to induce cell death." (PMID 27686855, 2016). "Interestingly, healthy people have cells expressing oncogenic KRAS in different organs, including the pancreas, colon, and lungs, at rates far exceeding the rates of cancer development." (PMID 27637077, 2016). "KRAS driver substitutions also predict response to targeted anti-cancer treatment." (PMID 26902163, 2016). "Similarly, no apparent increase in sensitivity to STLC was observed when using a different isogenic pair of cancer cell lines: SW48 KRAS+/+ and KRASG12D/+." (PMID 27412232, 2016). "Here we report that KRAS mutation may promote cancer cell proliferation by decreasing the expression of RCAN2, and that calcineurin and NFAT signaling may serve as potential therapeutic targets for KRAS-mutated CRC." (PMID 27526107, 2016). "This approach resulted in the identification of cell-surface proteins that have not previously been linked to constitutive KRas activation, along with proteins already described in the context of cancer cell lines expressing KRas mutants." (PMID 27894102, 2016). "In support of this hypothesis is the fact that other groups have also shown that antiapoptotic proteins are a potential target in KRAS-mutant cancers." (PMID 27634878, 2016). "Further study of this type of combination (for example, the dual inhibition of PLK1 and ROCK) against KRAS-mutant cancers in clinical trials may be warranted." (PMID 27193833, 2016). "Deep-sequencing of 538 cancer-relevant genes was carried out in 57 HD-ALL patients lacking the common KRAS and NRAS codon 12 or 13 hotspot mutations and common B-cell ALL deletions." (PMID 27683039, 2016). "Previous reports suggest KRAS-mutant cancer cells display abnormalities during mitosis." (PMID 27412232, 2016). "On the other hand, more information are available about NRAS and KRAS, in dog cancer." (PMID 26562302, 2015). "This classification also showed more frequent mutations in KRAS within distal nondiffuse cancers (12%) versus proximal nondiffuse (3%) and diffuse (0%) carcinomas (p = 0.12)." (PMID 25656989, 2015). "Because activating KRAS mutations are associated with poor LUAD prognosis and due to the current lack of reliable targeting agents, it is a clinical challenge to find efficient treatment strategies for KRAS-driven cancers." (PMID 26084335, 2015). "However, since most oncogenic mutations occur in the G domain of RAS, which is identical for KRAS4A and KRAS4B, KRAS4A should be activated in cancers harboring KRAS mutations." (PMID 26715448, 2015). "KRAS is an oncogene involved with the EGFR signaling pathway; KRAS activity in mCRC is associated with increased cell proliferation, angiogenesis, migration, and survival of the cancer tissue." (PMID 25888436, 2015). "It follows that, while targeting KRAS or its effector pathways provides a rational mechanism-based approach, a reasonable alternative is to identify pathways that are not directly regulated by KRAS but whose inactivation is lethal in cancer cells that harbor mutant KRAS." (PMID 26158412, 2015). "Moreover, some cancer cells can shuttle between the KRAS dependent (drug-sensitive) and independent (drug-tolerant) states and thus escape extinction." (PMID 26158412, 2015).
cancer (continued). "KRAS mutated patients were indicated to have a worse prognosis and resistance to treatment in different types of cancer but no clear conclusions have been stated for NSCLC18." (PMID 26573509, 2015). "Furthermore, stk33 has attracted attention since it has been identified as an essential component for the survival of KRAS-dependent cancer cells by high-throughput RNA interference (RNAi) screens." (PMID 26199010, 2015). "Importantly, we elucidated that knockdown of antioxidants significantly enhanced ROS generation, invasive and migratory properties and abnormal acini formation in KRAS transformed normal as well as cancer cells." (PMID 26515758, 2015). "Although KRAS mutations are associated with less efficient EGFR-directed targeted therapy in various cancer types, it is not yet known if the same is true in BTC." (PMID 26189560, 2015). "Similarly, the mutation of KRAS codon G12 has a VAF of 1, indicating that it occurred before the copy gain of chromosome 12p, timed at 21% of molecular cancer lifetime." (PMID 25768946, 2015). "With this approach, we found that the endogenous and ectopic expression of KRAS bearing the G13D mutation sensitizes normal, but not cancer cells, to CPT plus SM83 or TRAIL treatment, and to other DNA-damaging agents." (PMID 26028667, 2015). "We developed a novel mass spectrometry multiplexed genotyping platform named PentaPanel to concurrently assess single nucleotide polymorphisms in 56 hotspots of the 5 most clinically relevant cancer genes, KRAS, NRAS, BRAF, EGFR and PIK3CA for a total of 221 detectable mutations." (PMID 26435479, 2015). "Additionally, IQcs induce cancer cell death by apoptosis, explained in part by their capacity to repress KRAS expression." (PMID 25853628, 2015). "Together these mutations account for 95% of the nucleotide changes found in KRAS in human cancer." (PMID 26413866, 2015). "Upon treatment with EGFR-inhibiting antibodies such as Cetuximab or Panitumumab, patients showed an overall survival benefit of 3–5 months when the cancer was wildtype for KRAS, but no benefit when the cancer was KRAS-mutated." (PMID 26299805, 2015). "Next, we tested whether human KRAS-mutant cancer cells might specifically depend on the SWI/SNF complex." (PMID 25748138, 2015). "However, after recent discoveries relating to KRAS gene mutations in cancer patients, novel research strategies are focusing on circulating tumour DNA (ctDNA) and to the way that it might allow for a closer surveillance of the clinical evolution of cancer in certain types of patients." (PMID 26495028, 2015). "Because B-RAF is the major effector of KRAS, a B-RAF mutation might well be useful to predict the response to anti-EGFR therapy for cancers in patients with wild-type KRAS, as well as analysis of the KRAS mutation." (PMID 25908947, 2015). "Notably, mutant KRAS drives activation of cyclic-AMP response element-binding (CREB) through RAF/MEK/ERK signaling pathway to force cancer cell growth and survival." (PMID 25897662, 2015). "An analysis of the kinetics of KRAS mutation evolution in these patients further concluded that KRAS mutations had been present before anti-EGFR therapy initiation, in small subclones comprising ∼2000–3000 cancer cells." (PMID 25555261, 2015). "However, small populations of cancer cells can shuttle between the KRAS dependent (drug-sensitive) and independent (drug-tolerant) states and thus escape extinction." (PMID 26158412, 2015). "Although each mutated gene may be involved in tumorigenesis, only two mutations that we identified in the KRAS and CCDN1 genes are presently known to be functionally important for driving cancer." (PMID 26415226, 2015).
cancer (continued). "In our study, we demonstrated that using the BEAMing technology, testing for 21 oncogenic mutations in BRAF, EGFR, KRAS and PIK3CA genes in the plasma cfDNA of patients with advanced cancers referred for treatment with experimental targeted therapies, is feasible." (PMID 25980577, 2015). "This is most likely biologically meaningful as we observed a synergistic survival effect between CIP2A and RAS expression as well as KRAS activating mutations in TCGA pan-cancer data set, and synergistic relationship between CIP2A and KRAS depletion in colony growth assays." (PMID 26278961, 2015). "Moreover, it had received much more attention these years because of its high frequency of KRAS and BRAF mutations identified in certain human cancers and the critical role this pathway plays in promoting cell survival." (PMID 26347850, 2015). "In addition, there were no significantly difference in aspects of pT stage, pN stage and disease stage among KRAS-mutated, BRAF-mutated and wild type carcinomas." (PMID 25929517, 2015). "Exploration of recurrent alterations in the branches of carcinoma-specific mutations with distinct mutational contexts such as ERBB2 amplification preceding APC and KRAS mutations would also be valuable information for understanding the evolutionary process of CRC." (PMID 26336987, 2015). "The mean age at presentation for KRAS-mutated carcinoma was 57.7 ± 11.3 years, which was no significantly different to that for non-mutated-KRAS carcinoma at 57.3 ± 11.5 years and WT carcinoma cases at 57.1 ± 11.5 years." (PMID 25929517, 2015). "According to the current and our previously published studies, oxaliplatin-based regimens are more beneficial in KRAS mutant mCRC patients, because, theoretically, the earlier the effective regimens can be used, the greater probability cancers can be controlled." (PMID 24505265, 2014). "Although mutation of KRAS is frequently used for cancer diagnosis and clinical management, KRAS amplification is typically not tested in patients." (PMID 24874471, 2014). "As an example, we observed that KRAS showed a direct connection to numerous cancer-related pathways, such as MAPK signaling pathway, suggesting that it may be a central communication hub." (PMID 25137136, 2014). "Thus, transformation of a primary to a cancer cell involves a switch converting KRAS from an activator to a repressor of INK4-ARF." (PMID 24623306, 2014). "The combination of erlotinib and tivantinib (MET inhibitor) in NSCLC showed clinical activity in patients with KRAS-mutated cancers, even though the endpoints of the trial were not achieved." (PMID 24722523, 2014). "MiRNA-96 could directly downregulate the KRAS oncogene to restrain cancer cell invasiveness and immigration." (PMID 24587996, 2014). "The absence of correlations between KRAS mutational status and individual and family cancer history in LC and CRC patients included in our study is in agreement with previous studies." (PMID 25158139, 2014). "Despite widespread KRAS mutations in a variety of cancers, this protein has not been successfully targeted therapeutically; however, several approaches are being tested in clinical trials." (PMID 24722523, 2014). "KRAS mutations are one of the most commonly occurring oncogene aberrations in human carcinoma, but no specific treatment is currently available." (PMID 24782938, 2014). "Furthermore, it can quantitate the rare cancer mutant (KRAS codon 12) in a large excess of coexisting wild-type DNAs down to 0.75%." (PMID 23636707, 2013).
cancer (continued). "Low levels of let-7b and -c have been identified in different subtypes of AML, and the causal relationship of its deregulated expression in cancer can be supported by evidence suggesting it targets a number of genes involved in the cancer process such as KRAS, TRIM71, nRAS, MYC, and HMGA2." (PMID 24416592, 2013). "These could also explain why EGFR antibody treatment is initially effective to most KRAS wild-type cancer patients and then losts its efficiency as therapy continues." (PMID 23874486, 2013). "Using a protocol optimized for formalin-fixed tissues we achieved in situ mutation detection in routine FFPE sections, and prospective surgical cancer specimens with unknown KRAS status were successfully characterized." (PMID 24280411, 2013). "In our study, comparison of EML4-ALK fusion status with the presence of EGFR and KRAS mutations in the same cancer samples revealed that EML4-ALK fusions occurred in the absence of EGFR or KRAS mutations." (PMID 23341890, 2013). "We were also interested in evaluating NFE2L2 mRNA expression in relation to BRAF and KRAS mutations, since mutations to these genes occur frequently in PTC, and mutated KRAS and BRAF are associated with increased transcription of NFE2L2 in other cancers." (PMID 24138990, 2013). "Binary classification is the process of classifying objects within a group (cancer patients) into two subsets, cancer patients with mutations in KRAS, BRAF or NRAS, and cancer patients without mutations in these genes." (PMID 23991070, 2013). "A finding of potential interest is the significant prognostic impact of KRAS mutation in endometroid carcinomas, but not in other histological subtypes." (PMID 23800114, 2013). "Also, 2/5 (40%) of low-grade and 11/54 (20.4%) of high-grade carcinomas, with wild-type KRAS, showed MAPK positivity." (PMID 23388101, 2013). "New AREG/EREG-based predictive tests are urgently needed to identify wt KRAS cancer patients that may rapidly progress on Ctx owing to the selection of Ctx-resistant AREG/EREG-negative cells." (PMID 22491422, 2012). "All KRAS mutations detected in the present study have been previously reported in the Human Gene Mutation Database (HGMD) and in the Catalogue Of Somatic Mutations In Cancer (COSMIC)." (PMID 22931052, 2012). "Notably, genetic testing to guide cancer treatment, e.g., by assessing mutations in EFGR, KRAS, FLT3 and NPM is already established in other cancers." (PMID 23750322, 2012). "However, resistance to EGFR inhibitors often occurs, such as with KRAS mutant cancers, therefore new methods of targeting EGFR are needed." (PMID 23166750, 2012). "Likewise, KRAS has also been shown to be repressed by LET-7 in cancer cell lines resulting in reduced radio sensitivity." (PMID 22737227, 2012). "Whether these latent OIS programs can be activated in KRAS mutant cancers to result in a clinical effect has only recently been examined." (PMID 22654667, 2012). "Interestingly of the CIN cancers, the average FAL was significantly lower in KRAS mutant compared to KRAS wild type cancers (p = 0.045)." (PMID 23110075, 2012). "In addition to gene mutations, copy number alterations of EGFR, KRAS, PIK3CA and other signaling mediators are also critical factors that drive cancer development and determine prognoses and the sensitivity to anticancer drugs." (PMID 22994622, 2012). "Although KRAS mutations tend to activate the signal transduction pathways, not all KRAS mutations result in cancer formation." (PMID 22615799, 2012).
cancer (continued). "The difference in Abi1 expression between KRAS-muteted carcinoma and KRAS-mutated HPP, on the other hand, was not significant (p>0.1)." (PMID 22808230, 2012). "Our results point rather toward a cytoplasmic upregulation of Abi1 during colorectal tumorigenesis but interestingly, overexpression in KRAS-mutated carcinoma and metastasis was not significant compared to KRAS-mutated precursor lesions." (PMID 22808230, 2012). "Ras has many isoforms of which NRas and KRas are the most relevant to human cancer." (PMID 21479172, 2011). "We were able to show that Jass groups 1 and 2 definitely represent serrated adenocarcinomas, but KRAS-mutated cases belonging to Jass group 3 were composed of serrated and non-serrated cancers." (PMID 21457162, 2011). "The c12 G→A transitions were found in 52.6% (10/19) of KRAS-mutated serrated adenocarcinomas and in 12.5% (2/16; P = 0.047) of KRAS-mutated non-serrated cancers." (PMID 21457162, 2011). "The higher frequency of KRAS mutations was clearly more evident (although not statistically significant) in cancers with a residual serrated adenoma (57.1%, 16/28), being observed twice as often as BRAF mutations (28.6%, 8/28)." (PMID 21457162, 2011). "KRAS mutation was significantly more prevalent in carcinomas with MGMT methylation (46.3%) than in cases without MGMT methylation (46.3% vs. 28.5%; P = 0.006)." (PMID 21827707, 2011). "Finally, we have identified a number of down-regulated miRNAs whose targets are up-regulated in cancer, including the oncogenic protein KRAS and MYCN, mitogen-activated protein (MAP) kinases and the anti-apoptotic proteins BCL2, BCL2L2 and MCL-1 among others." (PMID 20668671, 2010). "Cancer cell lines with or without a known KRAS mutation were first used to test the HRMA methodology." (PMID 20959826, 2010). "Finally, we identified RBM47 and PTBP1 as regulators of KRAS E4 alternative splicing in cancer." (PMID 41368203, 2026). "However, most human cancers exhibit no mutations in KRAS, and this is also observed at measurable frequencies in COAD, LUAD, and PAAD." (PMID 41368203, 2026). "However, KRAS was initially considered an undruggable cancer target." (PMID 40829181, 2025). "While this framework is developed based on KRASG12C‐mutant LUAD, it lays the groundwork for potentially challenging the ‘one‐size‐fits‐all’ paradigm in KRAS‐driven cancers, and may inform biomarker‐driven combinatorial therapies as well as guide future clinical trial design." (PMID 41025426, 2025). "However, KRAS mutations, let alone KRASG12C mutation, account for only part of RAS-mutated cancers." (PMID 39506063, 2025). "However, those inhibiting PI3K-AKT-mTOR and KRAS-ERK/MAPK oncogenic pathways may suppress cancer and immune cells alike, leading to unintended consequences, like impaired T-cell function, and weakened immune responses." (PMID 40927720, 2025). "As previously reported and confirmed here, ADT-007 selectively induces apoptosis of KRAS-mutant cancer cells, which may be a key advantage over mutant-specific KRAS and other pan-KRAS or pan-RAS inhibitors approved or in development by circumventing resistance." (PMID 41008802, 2025). "These insights may pave the way for developing targeted therapies against KRAS-driven cancers." (PMID 39806421, 2025). "Inhibition of such proteins could provide therapies against KRAS‐related cancer." (PMID 40844185, 2025). "In addition, deletion of Atf3 in acinar cells altered expression of pathways involved in cancer progression through direct and indirect mechanisms, targeting positive and negative regulators of KRAS signaling that lead to decreased signaling through the MAPK pathway." (PMID 41198649, 2025). "However, a recent study on acute KRAS suppression in KRAS-mutant cells indicates that aberrant KRAS signaling drives cancer growth primarily through the MAPK-ERK pathway, influencing cell cycle progression at multiple levels including gene transcription and protein phosphorylation." (PMID 40860160, 2025).